MTOR (mechanistic target of rapamycin kinase)
Diseases named in the same sentence as MTOR in open-access papers (continued):
Sharing a sentence is not in itself a finding about the gene and the disease.
osteosarcoma (continued). "miR-451a promoted cell growth, migration, and EMT in osteosarcoma and activated the AKT/mTOR signalling pathway via YTHDC1-mediated m6A methylation." (PMID 38943031, 2024). "HSP90AA1 inhibited osteosarcoma cell apoptosis by deactivating the JNK/P38 pathway and promoted autophagic protection in response to chemotherapy by blocking the PI3K/AKT/mTOR signaling pathway, thus serving as an important regulator of osteosarcoma survival." (PMID 39430254, 2024). "For example, CLTC facilitates the oncogenesis and progression in osteosarcoma by activating the TGF-beta and AKT/mTOR signaling pathways." (PMID 39850878, 2024). "The application of activators targeting the PI3K/AKT/mTOR signaling pathway effectively reversed the impact of AIM2 overexpression on the proliferation, apoptosis, invasion, migration, and EMT of osteosarcoma cells." (PMID 39600708, 2024). "HSP90AA1 is also an important regulator of autophagy that promotes autophagy by mediating the PI3K/Akt/mTOR cascade and inhibits cell apoptosis through the JNK/P38 pathway in osteosarcoma." (PMID 39006030, 2024). "In osteosarcoma, OIP5-AS1 contributes to cisplatin resistance by inducing the LPAATβ/PI3K/Akt/mTOR pathway." (PMID 39401197, 2024). "Overall, TRIM22 promotes autophagic osteosarcoma cell death and inhibits osteosarcoma progression by promoting NRF2 proteasomal degradation, activating the ROS/AMPK/mTOR/autophagy signaling." (PMID 39062505, 2024). "In osteosarcoma, silencing HSP90B1 achieves tumor-suppressing effects on tumor growth, possibly through modulating the PI3K/AKT/mTOR pathway." (PMID 38711062, 2024). "Mechanistically, HSPD1 has been demonstrated to promote EMT and osteosarcoma progression by inhibiting ATP5A1 ubiquitination-dependent degradation and activating downstream AKT/mTOR signaling." (PMID 39430254, 2024). "Reports state that DRD2 on the cell membrane can inhibit tumor growth by downregulating eEF1A2, whereas eEF1A2 increases osteosarcoma progression and degradation by triggering the Akt/mTOR signaling pathway, highlighting DRD2's anti-osteosarcoma effects." (PMID 38586328, 2024). "In osteosarcoma, imbalance of the redox system induced JNK activation and mTOR inhibition mediate apoptosis and autophagy in the cells." (PMID 38586328, 2024). "In addition, in subtypes with mTOR overexpression or PTEN loss with alteration in the Rb-CDK4/6 pathway as a secondary driver such as leiomyosarcoma, angiosarcoma and osteosarcoma, combination therapies with CDK inhibitors and mTOR or PI3K inhibitors might be a potential therapeutic option." (PMID 38434982, 2024). "An important regulator of the PI3K/AKT/mTOR pathway is the well-known tumor suppressor PTEN: as in other cancers, also in osteosarcoma PTEN has been found suppressed, and its restoration has been proposed and studied for therapeutic purposes." (PMID 38534381, 2024). "We subcutaneously injected stably overexpressing 143B osteosarcoma cells into nude mice and observed that overexpression of RILP inhibited tumor growth by inhibiting the PI3K/AKT/mTOR pathway." (PMID 37789274, 2023). "mTOR inhibitors have been used in osteosarcomas, showing poor antineoplastic activity as monotherapy, probably due to the presence of many feedback loops in the IGF/PI3K/mTOR pathway." (PMID 37213274, 2023). "TRIM22 inhibits osteosarcoma progression by destroying NRF2 and activating ROS/AMPK/mTOR/autophagy signalling." (PMID 38037161, 2023). "Knockdown of S100A10 in the osteosarcoma cell line inhibited proliferation, migration, and invasion and induced apoptosis via the AKT/mTOR pathway by modulating glycolysis." (PMID 37892132, 2023). "Aberrant activation of the mTOR and MAPK pathways is responsible for the proliferative and oncogenic potential of numerous malignant phenotypes of osteosarcoma." (PMID 36681687, 2023).
osteosarcoma (continued). "Using RNA-seq data analysis, we uncovered the mechanism of action of RILP in osteosarcoma, at least in part, through its regulation of the PI3K/AKT/mTOR pathway, which in turn regulated the proliferation, migration, and invasion of osteosarcoma cells." (PMID 37789274, 2023). "Recent studies have reported that several signaling pathways (including the PI3K/Akt/mTOR, NF-κB, JAK/STAT, Hippo and hypoxia pathways) have an important role in cancer metastasis, including osteosarcoma 41-44." (PMID 36632453, 2023). "STEAP2 is also overexpressed in highly invasive osteosarcoma and subclone cell lines, and similar to EFEMP2, it also induces EMT through the PI3K/AKT/mTOR axis." (PMID 36316642, 2022). "As a dual PI3K and mTOR inhibitor, NVP-BEZ235 was reported to sensitize osteosarcoma and urothelial cancer cells to cisplatin by activating autophagic flux independent of apoptosis." (PMID 35211417, 2022). "Ginsenoside CK inhibits migration and invasion of human osteosarcoma cells and TGF-β-induced A549 cells via PI3K/mTOR/p70S6K1 and SIRT." (PMID 35893895, 2022). "Taken together, we concluded that AOS-SO4 suppressed osteosarcoma cell growth and promoted autophagy through the MEK1/ERK/mTOR signaling pathway in vivo." (PMID 35418575, 2022). "In this study, we demonstrated that the overexpression of lncRNA SOX21-AS1 upregulated mTOR and KLF4 through sponging hsa-mir-7-5p and hsa-mir-145-5p, and ultimately promoted osteosarcoma proliferation." (PMID 34696664, 2022). "Taken together, these data suggest that EFEMP2 induces EMT and initiates the PI3K/Akt/mTOR axis partly via its interaction with STEAP2, thereby enhancing the migratory and invasive capacities of osteosarcoma cells and promoting the development of osteosarcoma." (PMID 36316642, 2022). "Ginsenoside Rh2, a ginseng-derived compound, shows antiproliferation and apoptosis of osteosarcoma by activating mitogen-activated protein kinase (MAPK) and inactivating PI3K/AKT/mTOR and nuclear factor-κB (NF-κB)." (PMID 36139919, 2022). "Taken together, these findings indicate that EFEMP2 likely regulates EMT and activates the PI3K/AKT/mTOR axis by targeting STEAP2, thereby facilitating osteosarcoma cell infiltration and migration." (PMID 36316642, 2022). "Baicalin triggers apoptosis and autophagy of osteosarcoma cells by up-regulating ROS and down-regulating PI3K/AKT/mTOR." (PMID 36139919, 2022). "To our knowledge, this is the first study to explore the relationship between STEAP2 and osteosarcoma, and similar to EFEMP2 expression, we found that STEAP2 was also highly expressed in osteosarcoma and likely to affect EMT through the PI3K/AKT/mTOR axis." (PMID 36316642, 2022). "In summary, these findings reveal that baicalin activates ROS and Ca2+ and blocks the PI3K/Akt/mTOR, ERK1/2 and β-catenin pathways in osteosarcoma cells." (PMID 35573641, 2022). "While sole targeting of the IGF/PI3K/mTOR cascade has had limited success in early phase osteosarcoma trials, our study suggests that nuclear pIGF-1R might serve as a prognostic biomarker to identify osteosarcoma patients that have an especially poor prognosis." (PMID 35284040, 2022). "In osteosarcoma development, PI3K/Akt and its downstream signaling molecules mTOR and NF-κB constitute the PI3K/Akt/mTOR and PI3K/Akt/NF-κB pathways to regulate osteosarcoma through ERS." (PMID 36551309, 2022). "Our previous study revealed that EFEMP2 facilitates osteosarcoma infiltration and migration via its activation of the PI3K/Akt/mTOR axis and that changes in EFEMP2 expression induce similar changes in STEAP2 expression." (PMID 36316642, 2022). "To further investigate the anti-osteosarcoma mechanism of baicalin, we investigated its effects on the PI3K/Akt/mTOR, ERK1/2 and β-catenin signaling pathways." (PMID 35573641, 2022). "Our results prove that overexpression of lncRNA SOX21-AS1 up-regulates mTOR and KLF4 through sponging miR-7-5p and miR-145-5p, and ultimately promotes the proliferation of osteosarcoma." (PMID 34696664, 2022).
osteosarcoma (continued). "Our results demonstrate that the overexpression of lncRNA SOX21-AS1 up-regulates mTOR and KLF4 by sponging hsa-mir-7-5p and hsa-mir-145-5p, and ultimately regulates the proliferation of osteosarcoma." (PMID 34696664, 2022). "In our present study, we have successfully demonstrated the anti-osteosarcoma activity of 1,3,5-triazine derivatives as potent inhibitors of the PI3K/mTOR pathway." (PMID 35656180, 2022). "Knockdown of Aurora B promoted autophagy by decreasing mTOR/ULK1, and thereby suppressing osteosarcoma metastasis." (PMID 34585646, 2021). "Partial responses were registered in 3/24 (12.5%) osteosarcoma cases treated with a combination of anti-IGF1R mAb cixutumumab and the mTOR inhibitor tensirolibus." (PMID 34440844, 2021). "Mechanistically, we demonstrated that cordycepin enhanced the sensitivity of osteosarcoma cells to cisplatin by activating AMPK and inhibiting the AKT/mTOR signaling pathway." (PMID 34953496, 2021). "The present study demonstrates that a combination of an mTOR-VEGF inhibitor and a VEGFR inhibitor was effective for a DOX-resistant lung-metastatic osteosarcoma PDOX mouse model, at least in part due to strong anti-angiogenesis efficacy of the combination." (PMID 33883561, 2021). "In this study, we mainly discussed the autophagy induced by aloin in osteosarcoma cells and related PI3K/AKT/mTOR axis changes." (PMID 34819120, 2021). "Altogether, our results indicate that cordycepin augments the chemosensitivity of osteosarcoma cells to cisplatin by activating AMPK and suppressing the AKT/mTOR signaling pathway." (PMID 34953496, 2021). "Activation of the PI3K/AKT/mTOR axis was to be expected and MYC is a well known driver of osteosarcoma." (PMID 33295144, 2021). "As pro‐tumorigenic TGF‐β and AKT/mTOR signaling pathways were driven by CLTC in osteosarcoma, our study also encourages the development of TGF‐β inhibitors and AKT inhibitors for osteosarcoma therapy." (PMID 34185412, 2021). "Both Akt/mTOR and ERK1/2 axes mediate cell proliferation, migration, and inhibition of apoptosis in osteosarcoma." (PMID 32155954, 2020). "In osteosarcoma cells, PRDX1 promotes cell proliferation and metastasis through regulating Akt/mammalian target of rapamycin (mTOR) signaling pathway." (PMID 31956363, 2020). "RNA-seq analysis showed that the transcriptional signature of the U2OS osteosarcoma cell line is altered by the overexpression of TRIB2 and exposure to the PI3K/mTOR inhibitor BEZ235." (PMID 33316942, 2020). "Given the effective inhibition of PI3K/Akt/mTOR and Ras/Raf/MEK/ERK pathways, we explored pazopanib and trametinib antitumor activity in osteosarcoma preclinical models." (PMID 32531992, 2020). "Mammalian target of rapamycin (mTOR), is a downstream mediator in the PI3-K signalling pathway and is an essential serine/threonine kinase which is aberrantly activated in human osteosarcoma." (PMID 33370287, 2020). "Western blot analyses showed activation of main downstream signaling pathways (PI3K/Akt/mTOR and Ras/Raf/MEK/ERK) of expressed RTKs in all osteosarcoma cell lines." (PMID 32531992, 2020). "In osteosarcoma, Rh2 has an anticancer effect on U20S cells by regulating PI3K/Akt/mTOR signaling pathway." (PMID 33272245, 2020). "A subsequent phase II clinical trial was launched where patients with relapsed, unresectable osteosarcoma following standard MAP therapy were given both sorafenib and the mTOR inhibitor everolimus." (PMID 32961800, 2020). "In osteosarcoma drug resistance, few work has been done to show inhibition of autophagy by PI3K/Akt/mTOR pathway." (PMID 30153855, 2018).
osteosarcoma (continued). "To conclude, we report that PRDX1 is an important regulator of osteosarcoma carcinogenesis, in which PRDX1 promotes osteosarcoma cell proliferation, migration and metastasis by enhancing phosphorylation of Akt/mTOR." (PMID 29492195, 2018). "Here, we found that knockdown of PRDX1 suppress phosphorylation of Akt/mTOR/S6K in osteosarcoma cells, and overexpression of PRDX1 increase phosphorylation of Akt/mTOR/S6K." (PMID 29492195, 2018). "While the inhibition of mTOR expression and phosphorylation at S2448 by RAD001 has been proven in multiple cancer cell lines, an increase in phosphorylation at S2481 in osteosarcoma has also been described." (PMID 28591197, 2017). "Some of the drugs from our screen are already in clinical development for osteosarcoma (such as HDAC inhibitors), and an altered mTOR/PI3K/PTEN pathway was identified as a therapeutic target in 25% of tumors in a recently reported osteosarcoma genomic study." (PMID 28506242, 2017). "Consistent with earlier findings, TRIM14 increased p-AKT, p-mTOR and p-P70S6K levels in osteosarcoma cells, and blocking AKT activity reversed the TRIM14-induced promotory effects on cell growth and metastasis in the current study." (PMID 28205534, 2017). "A small molecule/kinase inhibitor screen of murine-derived osteosarcoma cell lines revealed activity in compounds (PIK-75, GSK2126458, and BEZ-235) targeting PI3K and mTOR and/or DNA-PK." (PMID 27441088, 2016). "Another study showed that cucurbitacin B inhibited the proliferation of seven human osteosarcoma cells lines in vitro, suppressing ERK, AKT, and mammalian target of rapamycin (mTOR) proteins." (PMID 25674792, 2015). "Downstream of Akt/mTOR signaling, we report increased expression levels of cathepsin K. TGF beta-induced cathepsin K secretion has been recently reported in human osteosarcoma cells." (PMID 25823658, 2015). "The function of miR-199a-3p and miR-34a in cell proliferation and apoptosis, it was clearly dependent on the presence of mTOR, MET and MDM4 gene in human osteosarcoma cells." (PMID 24957404, 2014). "The inhibition of mTOR signaling attenuated the cellular protection system and contributed to cell apoptosis in 4-HNE treated human osteosarcoma cell line MG63." (PMID 24711740, 2014). "We showed that miRNA signatures in response to a therapeutic agent (chemotherapy or the mTOR inhibitor RAD-001) were cell and drug specific on cell lines and a rat osteosarcoma model." (PMID 21437224, 2011). "In osteosarcoma, TRIM22 inhibits tumor progression via ROS/AMPK/mTOR-mediated autophagy activation." (PMID 40758712, 2025). "Research showed that PPARG antagonists could abnormally activate the PI3K/AKT/mTOR and ERK/mTOR pathways in osteosarcoma cells and effectively inhibited the growth of OS in vivo and in vitro." (PMID 40070565, 2025). "Therefore, according to this unique study, the AIM2 inflammasome seems to play an anti-tumor role in osteosarcoma, most likely via the PI3K/AKT/mTOR signaling pathway." (PMID 40002808, 2025). "Furthermore, common cancer-associated pathways such as the phosphatidylinositol 3-kinase/mammalian target of rapamycin (PI3K/mTOR) pathway and insulin-like growth factor (IGF) signaling have also been found to be abnormal in osteosarcoma." (PMID 38562379, 2024). "HSP90AA1, as an important regulator of autophagy, promoted autophagy through the PI3K/Akt/mTOR pathway, inhibited apoptosis through the c-Junction N terminal kinase (JNK)/P38 pathway, and was a critical factor in the development of osteosarcoma chemoresistance." (PMID 38713284, 2024). "About autophagy in osteosarcoma, the function of PI3K/Akt/mTOR signal pathway is complex." (PMID 38800967, 2024). "Through in vitro and in vivo experiments, we systematically identified HSPD1 as an important contributor to the regulation of proliferation, metastasis, and apoptosis in osteosarcoma by promoting the epithelial-mesenchymal transition (EMT) and activating AKT/mTOR signaling." (PMID 39430254, 2024).
osteosarcoma (continued). "The mammalian target of rapamycin (mTOR) plays an important role in osteosarcoma progression, as its pathway, the phosphatidylinositol 3-kinase (PI3K)/protein kinase B (AKT)/mTOR pathway, regulates a plethora of cellular processes, from cell growth and proliferation to metabolism and survival." (PMID 38534381, 2024). "Furthermore, COR inhibits osteosarcoma cell growth and invasion and induces osteosarcoma cell apoptosis by activating AMPK and inhibiting the AKT/mTOR signaling pathway and enhances the sensitivity of osteosarcoma cells to DDP." (PMID 39194034, 2024). "For example, FBXW7 (involved, as we have seen in this review, in mTOR and HIF ubiquitination) could be at the center of an activation strategy in osteosarcoma." (PMID 38534381, 2024). "In osteosarcoma development, the PI3K/AKT/mTOR signaling pathway can inhibit autophagy." (PMID 38800967, 2024). "Osteosarcoma cell glycolysis, proliferation, migration and invasion were suppressed by decreasing glycolysis-related proteins and migration-related proteins via the inhibition of c-MET and AKT3/mTOR." (PMID 38396845, 2024). "Notably, BKA blocked the effect of ATP5A1 overexpression on mTOR signaling in osteosarcoma cells, a finding that indicates the ATP generated by ATP5A1 overexpression is indispensable for mTOR activation." (PMID 39430254, 2024). "For solid tumor models, including brain tumors, the pan-PI3K inhibitor pilaralisib was tested against 38 models of multiple histologies, the PI3K and mTOR inhibitor voxtalisib was tested against 2 GBM models, and the pan-PI3K inhibitor copanlisib was tested against 6 osteosarcoma models." (PMID 39510293, 2024). "Absent in melanoma 2 (AIM2) and Fer-1-like protein 4 (FER1L4) are two osteosarcoma inhibitors, and several studies have found that their overexpression inhibited the PI3K/AKT/mTOR signaling pathway, with an increase in E-calmodulin and a decrease in wave proteins and fibronectin, inhibiting EMT." (PMID 37404761, 2023). "Additionally, HSP90AA1 can promote autophagy through the PI3K/Akt/mTOR signaling pathway, and inhibit apoptosis through the JNK/P38 signaling pathway to improve the drug resistance of osteosarcoma cells." (PMID 37999247, 2023). "Our findings suggest that PSMD14 may be an oncogenic gene that promotes osteosarcoma tumor growth and resistance to anlotinib by the PI3K/AKT/mTOR pathway." (PMID 38053170, 2023). "Our data showed that these chemicals may inhibit osteosarcoma cell proliferation by regulating the PI3K/AKT/mTOR and ERK/mTOR pathways." (PMID 36681687, 2023). "For instance, TRIM22 was found to inhibit osteosarcoma progression via destabilizing NRF2, which subsequently resulted in the imbalance of intracellular reactive oxygen species (ROS) and further activation of AMPK/mTOR/autophagy signaling." (PMID 37591850, 2023). "This discovery is consistent with human studies, where patients with acute myeloid leukaemia (AML) show reduced sesn expression and increased mTOR levels in peripheral blood and bone marrow, and T2A treatment reduces PI3K activity and increases sesn expression in related human osteosarcoma cells." (PMID 37202382, 2023). "The signaling pathways involved in tumor progression of Osteosarcoma are the FOXM1 transcription pathway, ATM signaling pathway, FAK mediated signaling events, Arf6 signaling events, Class 1 PI3K signaling events, mTOR signaling pathway, and Integrin family cell surface interactions." (PMID 37081847, 2023). "GPNMB may also be a potential target for targeted therapy of osteosarcoma, as it has been found that GPNMB can regulate the metastasis and proliferation of osteosarcoma cells by affecting the PI3K/AKT/mTOR pathway." (PMID 37404761, 2023). "Transcriptomic and immunoblotting results showed that these NR modulators may inhibit the growth of osteosarcoma cells by regulating the PI3K/AKT/mTOR and ERK/mTOR pathways." (PMID 36681687, 2023).